SRC (SRC proto-oncogene, non-receptor tyrosine kinase)
Diseases named in the same sentence as SRC in open-access papers (continued):
Sharing a sentence is not in itself a finding about the gene and the disease.
thyroid tumor (2 papers, 2018 to 2020). A benign or malignant neoplasm affecting the thyroid gland. "One recent report identified SRC kinases as targets for invasive thyroid tumors using kinase phosphorylation assay." (PMID 29455653, 2018).
uveal melanoma (2 papers, 2020 to 2025). A melanoma derived from melanocytes of the uveal tract. "A similar analysis of RPPA data from uveal melanoma (UM) tumors from TCGA (UVM-TCGA) also showed that tumors with BAP1 mutations have a decrease in SRC phosphorylation at Y527." (PMID 40754831, 2025). "Compensatory pathways are known to be activated in uveal melanoma, including HGF-c-Met, SRC, Ras, EGFR, VEGF, and phosphatidylinositol-3-kinase-AKT signaling." (PMID 32976223, 2020).
acute pancreatitis (1 paper, 2026). An acute inflammatory process that leads to necrosis of the pancreatic parenchyma. "Notably, elevated FAK/SRC-JNK signaling sensitizes cancer cells to ferroptosis-inducing therapies, while inhibition of the FAK/SRC-JNK signaling pathway protects against acute pancreatitis by suppressing ferroptosis." (PMID 41862445, 2026).
adenosquamous carcinoma (1 paper, 2018). A carcinoma composed of malignant glandular cells and malignant squamous cells. "Unexpectedly, profiling of in situ tumours demonstrated that signalling stratifies mostly according to histopathology, showing enhanced AKT and SRC activity in adenosquamous carcinoma, and mitogen‐activated protein kinase (MAPK) activity in adenocarcinoma." (PMID 29443392, 2018).
Anxiety (1 paper, 2022). Intense feelings of nervousness, tension, or panic often arise in response to interpersonal stresses. "In our study, 17 core common targets of ACG and anxiety were predicted, of which ESR1, SRC, AKT1, MAPK8, EGFR, and MMP9 belong to the prolactin and estrogen signaling pathways." (PMID 35624976, 2022). "Sarcoma tyrosine kinase (SRC) could mediate the phosphorylation of the NMDAR complex, and NMDAR2B phosphorylation could trigger anxiety-like behavior by regulating amygdaloid CRF expression." (PMID 35624976, 2022).
appendiceal neoplasm (1 paper, 2024). A benign or malignant neoplasm involving the appendix. "The CC score influenced survival more than any other factor in our data, and the appendiceal neoplasms showed better overall survival in the LAMN (G1) subgroup compared with the HAMN/MAC/SRC (G2/G3) subgroup." (PMID 39435876, 2024).
autoimmune hepatitis (1 paper, 2022). Hepatitis caused by autoantibodies. "As a consequence, 82 collective targets of celastrol and AIH were identified, among which PIK3R1, SRC, MAPK1, AKT1, and HRAS exhibited a closer association with autoimmune hepatitis." (PMID 35359864, 2022).
Batten disease (1 paper, 2018). "If, in the process of testing our hypothesis, increased levels of activated SFKs (e.g. SRC) will be found, a way to treat the juvenile form of Batten disease could be to use the SFK inhibitors." (PMID 30621751, 2018).
biliary tract cancer (1 paper, 2017). "Besides the mutation in MSH6, we identified 3 more mutations affecting genes described in cancer, but only rarely reported in biliary tract cancer (≤ 2%; SRC, MSN, PTPRC)." (PMID 28146430, 2017). "Moreover, in manual review of non-synonymous mutations, we identified a frameshift mutation in SRC, a gene encoding for a tyrosine kinase only rarely described to be mutated in biliary tract cancer and not present in the COSMIC cancer gene census." (PMID 28146430, 2017).
bone cancer (1 paper, 2019). A primary or metastatic malignant neoplasm affecting the bone or articular cartilage. "Subtoxic doses of eIF2α phosphatase GADD34/PP1c inhibitors guanabenz or salubrinal reduce breast and bone cancer cell migration/invasion through the reduction of SRC and RAC1 activity and through the modulation of MMP13 expression (for salubrinal)." (PMID 31064137, 2019).
bowel cancer (1 paper, 2025). "Considering the regulatory roles of cancer-related KEGG pathways and key targets, such as the influence of SRC on bowel cancer cells, we propose that PPDs and PPDQs may significantly affect both the incidence and metastasis of bowel cancer." (PMID 40559953, 2025).
brain cancer (1 paper, 2016). A primary or metastatic malignant neoplasm affecting the brain. "Previous studies have strongly implicated the non-receptor tyrosine kinase SRC in the development, maintenance, progression, and invasiveness of several human cancers, including brain cancers." (PMID 26700818, 2016).
chordoma (1 paper, 2021). Chordomas are rare malignant tumors arising from embryonic remnants of the notochord in axial skeleton. "Also, several oncogenes such as BCL2 (11.5-fold), BRAF (9.8-fold), KRAS (4.9-fold), and SRC (2.8-fold) are significantly stronger expressed in the recurrent chordoma cell line." (PMID 34330313, 2021).
chronic neutrophilic leukemia (1 paper, 2021). A rare chronic myeloproliferative neoplasm characterized by neutrophilic leukocytosis. "Additionally, in a study on chronic neutrophilic leukemia (CNL) and atypical (BCR-ABL1–negative) CML in patients with CSF3R mutations, CSF3R truncating mutations were found to be sensitive to dasatinib suggesting that the trial of SRC kinase inhibitors is a reasonable approach." (PMID 34771705, 2021).
Cirrhosis (1 paper, 2022). A chronic disorder of the liver in which liver tissue becomes scarred and is partially replaced by regenerative nodules and fibrotic tissue resulting in loss of liver function. "In cirrhosis patients and thioacetamide (TAA)-induced fibrotic mice livers, SRC expression was shown to be increased, and phospho-SRC was elevated after the activation of hepatic stellate cells." (PMID 36297027, 2022).
co-infection (1 paper, 2025). "Subsequently, we obtained the top 16 hub targets of probenecid for SARS-CoV-2/RSV co-infection, namely, AKT1, ALB, EGFR, CASP3, CTNNB1, SRC, HSP90AA1, and so on." (PMID 40371107, 2025). "Therefore, SRC and EGFR may serve as key targets for probenecid in treating SARS-CoV-2/RSV co-infection, while HSP90AA1 may play a lesser role." (PMID 40371107, 2025).
colorectal polyps (1 paper, 2016). "c-SRC expression is reported to be 5–8 fold higher in premalignant colorectal polyps than in normal mucosa and a correlation between elevated c-SRC levels and CRC progression/metastatic potential has been suggested." (PMID 27562229, 2016).
diabetic retinopathy (1 paper, 2022). "Molecular docking confirmed a good binding affinity of active ingredients of Mingmu Dihuang pill, including luteolin, acacetin, naringenin, and alisol B, with AKT1, SRC, and VEGFA, three hub targets of diabetic retinopathy." (PMID 36467890, 2022). "Molecular docking confirmed a good binding affinity of active ingredients of MMDHP, including luteolin, acacetin, naringenin, and alisol B, with AKT1, SRC, and VEGFA as the three key targets of diabetic retinopathy." (PMID 36467890, 2022). "AKT1, SRC, and VEGFA were found to have the binding energy of < −5 kcal/mol with all key targets of diabetic retinopathy, suggesting the good binding energy towards the key targets of diabetic retinopathy." (PMID 36467890, 2022). "MMDHP may be effective for the treatment of diabetic retinopathy through active ingredients luteolin, acacetin, naringenin, and alisol B via AKT1, SRC, and VEGFA in AGE-RAGE, PI3K-AKT, and Rap1 signaling pathways." (PMID 36467890, 2022). "In summary, the results of the present study demonstrate that Mingmu Dihuang pill may be effective for the clinical treatment of diabetic retinopathy through active ingredients luteolin, acacetin, naringenin, and alisol B via AKT1, SRC, and VEGFA in AGE-RAGE, PI3K-AKT, and Rap1 signaling pathways." (PMID 36467890, 2022).
ductal carcinoma (1 paper, 2009). "Also, expression of oncoproteins with anti-apoptotic activities, including receptor tyrosine kinase ErbB2, colony-stimulating factor 1 receptor, SRC, and IGF1R, has been shown to elicit abnormal, filled phenotypes that resemble human ductal carcinoma in vivo." (PMID 20043854, 2009).
eating disorder (1 paper, 2022). A broad group of psychological disorders with abnormal eating behaviors leading to physiological effects from overeating or insufficient food intake. "Moreover, the malfunction of signaling molecules in the CCK/SRC/PI3K cascade reaction with leptin/JAK2/PI3K/STAT3 signaling pathway may lead to eating disorders." (PMID 36359184, 2022).
endometrial disorder (1 paper, 2014). A non-neoplastic or neoplastic disorder that affects the endometrium. "Though descriptive, these clinical findings propose a causal link between elevated expression of SRC-2 (as well as other SRC members) and the emergence of these endometrial disorders." (PMID 24905738, 2014).
endometrial tumor (1 paper, 2016). "Taken as a whole, from the view of the cancer microenvironment, an up-regulation of NMU signaling in progressive endometrial tumor cells would also help these malignant cells become more sensitive to niche growth factors such as EGF and TGFβ via the adhesion signaling-SRC cascades." (PMID 26849234, 2016).
Familial adenomatous polyposis (1 paper, 2015). Familial adenomatous polyposis (FAP) is characterized by the development of hundreds to thousands of adenomas in the rectum and colon during the second decade of life. "Increased SRC expression is observed in intestinal adenomas of the ApcMin mouse model of familial adenomatous polyposis, suggesting that the WNT/β-catenin pathway may contribute to increased SRC signaling." (PMID 26087188, 2015).
gastric tumor (1 paper, 2015). "We found elevated expression of SRC and LYN kinase mRNA and protein but decreased levels of CKB kinase, alterations that may have a role in the invasiveness and metastasis of gastric tumors." (PMID 26460485, 2015). "Moreover, as for SRC, LYN may also have a role in gastric tumor invasiveness, metastasis, and thus aggressiveness." (PMID 26460485, 2015).
Graves disease (1 paper, 2023). Graves' disease is an autoimmune disorder that leads to overactivity of the thyroid gland (hyperthyroidism).It is caused by an abnormal immune system response that causes the thyroid gland to produce too much thyroid hormones. "Multiple studies indicated that SRC regulated the PI3K-AKT pathway in inflammation-related diseases such as multiple sclerosis (MS), Grave’s Disease (GD), and in the neutrophil extracellular traps (NET) formation." (PMID 37163367, 2023).
Inguinal hernia (1 paper, 2024). Protrusion of the contents of the abdominal cavity through the inguinal canal. "Thus, SRC mutations may lead to abnormal type I collagen or abdominal wall defects via the TGF-β/PI3K/Akt signaling pathway, resulting in inguinal hernias." (PMID 38591204, 2024).
ischemic disease (1 paper, 2025). Lack of blood supply to an area of the body, resulting in impairment of tissue oxygenation. "In ischemic diseases, SRC activation has been found to correlate with changes in ROS levels, and the Nrf2/HO-1 signaling pathway is considered a crucial pathway related to oxidative stress." (PMID 40784044, 2025).
lactic acidosis (1 paper, 2023). Metabolic acidosis characterized by the accumulation of lactate in the body. "We also checked the S-glutathionylation of G6PD and SRC under lactic acidosis." (PMID 37491277, 2023). "Previous paper reported that GSTP1 promoted the S-glutathionylation of SRC under TNF-α stimulation, but is not found under lactic acidosis in our paper." (PMID 37491277, 2023).
listeriosis (1 paper, 2022). A bacterial infection caused by Listeria monocytogenes. "Therefore, these compounds could be considered for use as a potential treatment for listeriosis by inhibiting proteins such as, IL2, MAPK1, SRC, EGFR, PTPRC, TNF, IL1B, and ERBB2." (PMID 36671206, 2022).
lung diseases (1 paper, 2022). "In addition, in vitro and in vivo experiments in which inhibitory effects on pulmonary fibrogenesis were observed using specific SRC kinase inhibitors corroborate the crucial role of SRC for the development of variant fibrotic lung diseases." (PMID 35203313, 2022).
lymphangioleiomyomatosis (1 paper, 2021). A multifocal neoplasm with perivascular epithelioid cell differentiation affecting almost exclusively females of child-bearing age. "Another phase II study is investigating this molecule as a SRC inhibitor in lymphangioleiomyomatosis, with a regimen of 125 mg daily for 9 months (NCT02737202)." (PMID 33705358, 2021).
lymphopenia (1 paper, 2018). Reduction in the number of lymphocytes. "We also observed that lymphopenia was temporally associated with the upregulation of CCR2, LYN, PAK1, PTK2B, SRC, STAT3, which are involved in the chemokine signaling pathway." (PMID 30713538, 2018).
Lynch syndrome (1 paper, 2022). An autosomal dominant hereditary neoplastic syndrome characterized by the development of colorectal carcinoma and a high risk of developing endometrial carcinoma, gastric carcinoma, ovarian carcinoma, renal pelvis carcinoma, and small intestinal carcinoma. "However, EGFR and SRC genes were found in the LP, non-P, and non-Lynch syndrome groups, but not in the P group, thus suggesting substantial differences in the protein interaction network." (PMID 35014770, 2022).
malaria (1 paper, 2025). Malaria is a serious and sometimes fatal disease caused by a parasite that commonly infects a certain type of mosquito which feeds on humans. "Compared with that in the malaria group, the expression level of protein SRC in the spleen of the ZF-CQ group was significantly higher (P< 0.05)." (PMID 41425569, 2025). "Western blotting results indicated that the expression levels of proteins SRC and PKC in the spleens of the malaria group decreased significantly (P< 0.01 or< 0.05, respectively) compared with those in the control group." (PMID 41425569, 2025).
mantle cell lymphoma (1 paper, 2020). Mantle cell lymphoma is a rare form of malignant non-Hodgkin lymphoma affecting B lymphocytes in the lymph nodes in a region called the ``mantle zone''. "Particularly, MK-1775 enhances the efficacy of SRC inhibitors in BL, and the combination of CHK1 and WEE-1 inhibitors is synergistic in mantle cell lymphoma." (PMID 31836849, 2020).
metastasis (1 paper, 2019). The spread or migration of cancer cells from one part of the body (where they first appeared) to another. "In terms of clinicopathological characteristics, SRC mutation was significantly associated with left-sided tumor and liver metastasis compared to BRAF V600E mutation (P = 0.016 and P = 0.025, respectively)." (PMID 30792536, 2019).
metastatic cancer (1 paper, 2020). A carcinoma which has spread from the original site of growth to another anatomic site.
metastatic prostate carcinoma (1 paper, 2024). A carcinoma that arises from the prostate gland and has spread to other anatomic sites. "The activation of SRC will contribute to the development of primitive and metastatic prostate cancer." (PMID 39771106, 2024).
migraine (1 paper, 2021). "Three of the DE genes were DE after cold pressor test (i.e. C vs D) and were therefore not considered to be migraine genes (LUC7L3, SRC and RPGR)." (PMID 33859262, 2021).
myeloid tumor (1 paper, 2021). "In preclinical studies, BCL-2 and SRC inhibitors have been shown to eradicate senescent myeloid tumor cells and have already been tested in AML." (PMID 33557090, 2021).
myeloproliferative neoplasm (1 paper, 2015). A clonal hematopoietic stem cell disorder, characterized by proliferation in the bone marrow of one or more of the myeloid (i.e., granulocytic, erythroid, megakaryocytic, and mast cell) lineages. "Although the dual BCR-ABL/SRC TKI dasatinib inhibits the kinase activity of KIT D816V in vitro and has demonstrated efficacy in other myeloproliferative neoplasms, such as CML, it has displayed minimal activity in patients with SM." (PMID 26002753, 2015).
myosarcoma (1 paper, 2022). "Actually, earlier studies have shown that when the SRC oncogene is inactivated, the SRC-induced myosarcoma cells will differentiate into mature myocytes 502-504, and this inactivation-caused differentiation is actually a common event for SRC-caused transformation." (PMID 35912015, 2022).
ovarian adenocarcinoma (1 paper, 2021). An adenocarcinoma that arises from the ovary. "Saracatinib (AZD0530) is a potent, orally bioavailable SRC/ABL inhibitor originally developed by AstraZeneca for treatment of ovarian adenocarcinoma." (PMID 33705358, 2021).
papilloma (1 paper, 2015). A benign epithelial neoplasm that projects above the surrounding epithelial surface and consists of villous or arborescent outgrowths of fibrovascular stroma. "Moreover authors observed that when coupling phosphoproteomics and prediction of kinase activity, in this research study, PAK4-PKC/SRC network was highly deregulated in SCC although it was not in papilloma." (PMID 26055493, 2015).
Peptic ulcer (1 paper, 2024). The term peptic ulcer refers to acid peptic injury of the digestive tract, resulting in mucosal break reaching the submucosa. "The PPI network was constructed for the peptic ulcer genes, the constructed network to show the interactions between peptic ulcer targets proved that the following genes have the higher node degrees; AKT1, TNF, SRC, EGFR, ESR1, PTGS2, MMP9." (PMID 38728332, 2024).
polycystic kidney disease (1 paper, 2015). A usually autosomal dominant and less frequently autosomal recessive genetic disorder characterized by the presence of numerous cysts in the kidneys leading to end-stage renal failure. "This interpretation would be compatible with the limited activity of inhibitors of the S6 activator mTOR, or inhibitors of SRC, in assessment for treatment of polycystic kidney disease." (PMID 26528438, 2015).
postpartum depression (1 paper, 2025). A type of clinical depression that occurs after childbirth. "The level of SRC was reduced in mice model of postpartum depression, that subsequently decreased tyrosine phosphorylation of NMDA receptors and impaired the hippocampal neurogenesis." (PMID 39936089, 2025).
preeclampsia (1 paper, 2021). Preeclampsia is a hypertensive disorder of pregnancy that is characterized by new-onset hypertension with proteinuria presenting after 20 weeks of gestation, and depending on mild or severe forms may initially present with severe headache, visual disturbances, and hyperreflexia. "Women with preeclampsia showed an elevated level of SRC protein, but the activation by the phosphorylation in the Tyr-416 residue was lowered, suggesting a low activation compared with normal women." (PMID 34867473, 2021). "Downstream genes activated by SRC, including ERK1/2, p38, and JNK showed low phosphorylation in preeclampsia, demonstrating the inactivation of SRC or c-SRC, which are critical for trophoblast development and differentiation." (PMID 34867473, 2021).
Renal cyst (1 paper, 2023). A fluid filled sac in the kidney. "In ADPKD, signaling pathways activated in renal cysts by loss of PKD1 include many known to be activated and growth-promoting in cancer including WNT/CTNNB1, PI3K/AKT, mTOR/S6K, RAF/MEK/ERK, SRC, MYC, AURKA, and others." (PMID 37542051, 2023).
rhabdomyosarcoma (1 paper, 2018). A rare aggressive malignant mesenchymal neoplasm arising from skeletal muscle. "Similarly, a combination of anti-IGF-1R and SRC therapies displayed enhanced antitumour activity in in vitro and in vivo models of rhabdomyosarcoma when compared to either drug alone." (PMID 29435137, 2018).
sarcoidosis (1 paper, 2022). Sarcoidosis is a multisystemic disorder of unknown cause characterized by the formation of immune granulomas in involved organs. "In line with these previous studies, SRC showed a higher expression in sarcoidosis lungs in our study." (PMID 35203313, 2022).